ZBTB7A (zinc finger and BTB domain containing 7A)
Diseases named in the same sentence as ZBTB7A in open-access papers (continued):
Sharing a sentence is not in itself a finding about the gene and the disease.
lung adenocarcinoma (5 papers, 2019 to 2023). A carcinoma that arises from the lung and is characterized by the presence of malignant glandular epithelial cells. "The histone reader protein HP1γ could modulate the epigenetic suppression of the transcription‐repressive regulators NCOR2 and ZBTB7A to activate the protumorigenic transcriptome in lung adenocarcinoma." (PMID 36504353, 2023). "Alam etal. demonstrated that CBX3/HP1γ promoted proliferation, colony formation, and migration in lung adenocarcinoma (LUAD) cells by directly repressing NCOR2 and ZBTB7A." (PMID 31375643, 2019). "Moreover, CBX3 facilitates the progression of lung adenocarcinoma by directly repressing NCOR2 and ZBTB7A expression." (PMID 34395271, 2021).
endometrial cancer (4 papers, 2016 to 2024). Primary or metastatic malignant neoplasm involving the endometrium (mucous membrane that lines the endometrial cavity). "A recent study found that ZBTB7A can impede the proliferation and migration of endometrial cancer cells and is positively associated with a more favorable prognosis for endometrial cancer." (PMID 38981872, 2024). "In the case of ZBTB7A, its reduced expression in endometrial cancer is associated with unfavorable overall survival and disease-free survival." (PMID 35163161, 2022). "Enhanced expression of ZBTB7A markedly suppressed the growth, metastasis, and angiogenesis of endometrial cancer cells in both tumor metastasis and xenograft models in vivo." (PMID 38981872, 2024). "To conclude, the findings imply that the enhanced expression of SOX17 considerably reduces the suppressive impact of ZBTB7A on malignant biological activities in endometrial cancer cells." (PMID 38981872, 2024). "Significant reduction in mRNA expression and DNA copy number variation of ZBTB7A was noted in endometrial cancer compared to the control." (PMID 35163161, 2022). "The reduced ZBTB7A level in endometrial cancer was observed in analyses using the UALCAN and Oncomine databases and was validated with the GEPIA database." (PMID 35163161, 2022). "In turn, the ZBTB7A expression was low in endometrial cancer tissues grouped according to cancer stage, age, and race compared to the control group." (PMID 35163161, 2022). "Our study systematically applied public database to guide the research of ZBTB7A in endometrial cancer." (PMID 33292231, 2020). "Therefore, our results reveal ZBTB7A as a new target and direction for the diagnosis and treatment of endometrial cancer." (PMID 33292231, 2020). "ZBTB7A inhibits proliferation and migration of endometrial cancer cells." (PMID 33292231, 2020). "Finally, CCK8, migration, ChIP assays were introduced to partly validate ZBTB7A function in endometrial cancer cells." (PMID 33292231, 2020). "In Sum, ZBTB7A could be identified as an important potential biomarker for endometrial cancer." (PMID 33292231, 2020). "Next, we explored whether ZBTB7A affects biological function of endometrial cancer cells." (PMID 33292231, 2020). "Our results indicate that ZBTB7A may be a new potential prognostic marker in endometrial cancer." (PMID 33292231, 2020). "Our subsequent investigation focused on the impact of SOX17 overexpression on the restraining effect of ZBTB7A on malignant biological behaviors in HEC-1 A and KLE endometrial cancer cell lines." (PMID 38981872, 2024). "The observed low ZBTB7A expression resulted in unfavorable overall survival and disease-free survival (DFS) in patients with endometrial cancer." (PMID 35163161, 2022). "Our work determine that ZBTB7A is notably downregulated in UCEC, inhibits proliferation and migration in endometrial cancer cells, serves as an indicator for favorable prognosis and immune infiltration." (PMID 33292231, 2020). "Besides, we verify that ZBTB7A can repress the transcription of E2F4, which may be responsible for function of ZBTB7A in endometrial cancer." (PMID 33292231, 2020). "Based on our comprehensive analysis, we propose the following hypothesis: The transcription factor ZBTB7A suppresses the expression of ELAVL1 by transcriptionally inhibiting LncRNA HOTAIR, which in turn inhibits the malignant biological behavior and angiogenesis in endometrial carcinoma." (PMID 38981872, 2024).
hepatocellular carcinoma (4 papers, 2017 to 2025). A malignant tumor that arises from hepatocytes. "However, it has been found that miR-106b targeting of ZBTB7A increases the survival of hepatocellular carcinoma cells." (PMID 32083004, 2020). "MiR-125a expression is downregulated in several tumors, including hepatocellular carcinoma (HCC) where it targets sirtuin-7, matrix metalloproteinase-11, VEGF-A, Zbtb7a, and c-Raf." (PMID 28878257, 2017).
melanoma (4 papers, 2017 to 2022). A malignant, usually aggressive tumor composed of atypical, neoplastic melanocytes. "ZBTB7A is known to promote metastasis in melanoma and TP63 is associated with resistance to therapeutic agents." (PMID 28472408, 2017). "In particular, downregulation of ZBTB7A or TP63 has already been associated with poor prognosis of melanoma patients." (PMID 28472408, 2017). "For this purpose, we utilized fresh-frozen sections and FFPE sections from a mouse xenograft of melanoma to detect circPOK, a circular RNA produced from the ZBTB7a gene (also known as leukemia release factor, LRF)." (PMID 35053590, 2022). "In addition, ZBTB7A, a ZF-C2H2 TF with a 2.3-fold decrease in gainability in skin cancer, suppresses melanoma metastasis." (PMID 33077858, 2020).
bladder cancer (3 papers, 2022 to 2025). "The role of ZBTB7A in bladder cancer was detected by colony formation, transwell, and tumor formation assays." (PMID 35501800, 2022). "Although ZBTB7A has been shown to act as an oncogenic or tumor suppressor protein in a variety of malignancies, its role and regulation mechanism in bladder cancer are poorly understood." (PMID 35501800, 2022). "Our study revealed that miR-144-3p decreased ZBTB7A expression in bladder cancer." (PMID 35501800, 2022). "However, the function and molecular mechanism of ZBTB7A in bladder cancer (BC) remain elusive." (PMID 35501800, 2022). "In bladder cancer, ZBTB7A can bind to the HIC1 promoter, and decreased HIC1 expression can promote the malignant behavior of bladder cancer cells." (PMID 37388742, 2023).
cholangiocarcinoma (3 papers, 2017 to 2020). A carcinoma that arises from the intrahepatic biliary tree (intrahepatic cholangiocarcinoma) or from the junction, or adjacent to the junction, of the right and left hepatic ducts (hilar cholangiocarcinoma). "However, miRNA-106-5p can sensitize cholangiocarcinoma cells to 5-fluorouracil by targeting zinc finger and BTB domain containing 7A (ZBTB7A)." (PMID 32756339, 2020).
non-small cell lung carcinoma (3 papers, 2019 to 2022). A group of at least three distinct histological types of lung cancer, including non-small cell squamous cell carcinoma, adenocarcinoma, and large cell carcinoma. "ZBTB7A has been reported can enhance the development of non-small cell lung cancer by activating the Wnt/β-catenin pathway." (PMID 34304709, 2021). "Moreover, ZBTB7A can regulate the activity of Wnt signaling pathway in non-small cell lung cancer cells and thereby accelerating the cancer progression." (PMID 34304709, 2021).
acute kidney injury (2 papers, 2023). Sudden and sustained deterioration of the kidney function characterized by decreased glomerular filtration rate, increased serum creatinine or oliguria. "Noteworthy is that transcription factor ZBTB7A positively regulated the proliferative inhibiting impact of KLF10 in acute kidney injury (AKI)." (PMID 37107656, 2023).
beta thalassemia (2 papers, 2024 to 2025). Beta-thalassemia (BT) is characterized by deficiency (Beta+) or absence (Beta0) of synthesis of the beta globin chains of hemoglobin (Hb). "LRF/ZBTB7A gene expression levels in patients who received hydroxyurea treatment (homozygous SCA or combined heterozygous sickle cell/beta thalassemia) were found to be lower than those in patients who responded to treatment, as expected." (PMID 41413825, 2025).
Intellectual disability (2 papers, 2023 to 2026). "ZBTB7A encodes a transcription factor, variants of which cause a neurodevelopmental disorder characterized by intellectual disability, macrocephaly, and overgrowth of adenoid tissue." (PMID 40836029, 2026).
liver fibrosis (2 papers, 2023 to 2024). "For example, miR-342-3p was found to regulate hepatic stellate cell (HSC) activation by affecting the Zbtb7a-mediated TGF-β signaling in a model of Echinococcus multilocularis infected liver fibrosis." (PMID 39379100, 2024). "Therefore, mmu-miR-342-3p is a key regulator for activation of HSCs, and inhibiting mmu-miR-342-3p to suppressed Zbtb7a-mediated TGF-β signaling in activated HSCs could be a novel strategy to treat liver fibrosis induced by E. multilocularis." (PMID 37490505, 2023).
lung cancer (2 papers, 2018 to 2025). A malignant neoplasm involving the lung. "ZBTB7A is a tumor suppressor, which is involved in several cancers such as prostate and nonsmall cell lung cancers." (PMID 29686831, 2018).
lymphoma (2 papers, 2021 to 2022). A malignant (clonal) proliferation of B- lymphocytes or T- lymphocytes which involves the lymph nodes, bone marrow and/or extranodal sites. "Diseases associated with ZBTB7A include photosensitive epilepsy and lymphoma." (PMID 33836777, 2021).
nasopharyngeal carcinoma (2 papers, 2019 to 2025). A carcinoma arising from the nasopharyngeal epithelium. "Our previous studies showed that ZBTB7A played an important role in promoting nasopharyngeal carcinoma (NPC) progression." (PMID 31309112, 2019).
T-cell lymphoma (2 papers, 2016 to 2021). "Despite barely detectable in normal thymic CD3+ T cells, ZBTB7A is highly expressed in a subset of human T-cell lymphoma, and its overexpression induces the development of a mouse precursor T-cell lymphoma by directly repressing the transcription of the tumor suppressor gene Cdkn2a (Arf)." (PMID 34349770, 2021).
anemia (1 paper, 2022). A reduction in the number of red blood cells, the amount of hemoglobin, and/or the volume of packed red blood cells. "Zbtb7a-/-mice models are embryonic lethal due to anemia, whereas the conditional knockout of Zbtb7a in adult mice leads to mild macrocytic anemia following inefficient terminal erythropoiesis." (PMID 35741383, 2022).
breast tumors (1 paper, 2020). "Mechanically, ZBTB7A could act as a tumor suppressor by directly binding to the ERα promoter in ERα-positive breast tumors." (PMID 33167891, 2020).
cataract (1 paper, 2021). Partial or complete opacity of the crystalline lens of one or both eyes that decreases visual acuity and eventually results in blindness. "Here, the expression of ZBTB7A in lens capsules of cataract patients and normal people was detected." (PMID 34304709, 2021). "In this research, KLF1 was also found to promote the expression of ZBTB7A in lens capsule tissues of cataract patients and human lens epithelial cells." (PMID 34304709, 2021). "The immunohistochemistry results also showed the expression of ZBTB7A was enhanced in lens capsule tissues of cataract patients compared to the normal people." (PMID 34304709, 2021).
depression (1 paper, 2025). "Using cross-species epigenomic profiling and rodent models, they show that astrocytic ZBTB7A reshapes neuronal activity and behavior following stress, revealing a glial-mediated epigenetic mechanism of depression vulnerability." (PMID 40516534, 2025).
dilated cardiomyopathy (1 paper, 2019). Cardiomyopathy which is characterized by dilation and contractile dysfunction of the left and right ventricles. "Similarly, Qiao’s study also reported that SPI1, ZBTB7A, and IRF8 play crucial roles in the development of dilated cardiomyopathy and ischemic cardiomyopathy by regulating inflammation- and apoptosis-related genes." (PMID 31850068, 2019).
head and neck cancer (1 paper, 2020). A primary or metastatic malignant neoplasm affecting the head and neck. "Database analysis indicates that the expression level of and the copy status of ZBTB7A and TRAIL-R2 are important survival predictors for head and neck cancers." (PMID 32083004, 2020).
lymph node metastasis (1 paper, 2020). "On the contrary, higher expression of ZBTB7A was associated with lymph node metastasis and higher Duke’s stage in a previous study." (PMID 33167891, 2020).
Macrocephaly (1 paper, 2025). Occipitofrontal (head) circumference greater than 97th centile compared to appropriate, age matched, sex-matched normal standards. "Mutations in the LRF/ZBTB7A gene are responsible for macrocephaly, neurodevelopmental delay, lymphoid hyperplasia, and persistent fetal hemoglobin (MNDLFH, OMIM #619769)." (PMID 41413825, 2025).
metastatic tumors (1 paper, 2025). "After confirming the regulatory role of TMED3 on ZBTB7A in vitro, we further validated ZBTB7A expression in clinical specimens and metastatic tumors through hematoxylin and eosin (H&E) staining and immunofluorescence." (PMID 40471367, 2025).
myeloid leukaemia (1 paper, 2016). "The favourable prognostic relevance of high ZBTB7A expression in CN-AML, which accounts for half of all AML patients, may point towards a more general tumour suppressor role of ZBTB7A in myeloid leukaemia." (PMID 27252013, 2016).
ovarian carcinoma (1 paper, 2025). A malignant neoplasm originating from the surface ovarian epithelium. "Copy number alterations in genes such as PDCD10 and NDUFB9 (amplifications) and NDUFS7 and ZBTB7A (deletions) were also identified, particularly in ovarian cancer, suggesting their contributions to genomic instability." (PMID 40396172, 2025).
pancreatic adenocarcinoma (1 paper, 2015). "Significant positive correlations were also observed in the Collisson Pancreatic adenocarcinoma (cancer only) dataset between ZBTB7A and Src." (PMID 26187947, 2015).
prostate adenocarcinoma (1 paper, 2023). "Utilizing informatic modeling of whole transcriptome sequencing data from patient samples, we identified distinct gene networking patterns of ZBTB7A in NEPC versus prostate adenocarcinoma." (PMID 37065756, 2023). "The discrepancy of RET and ZBTB7A dependency in SCN HI versus SCN LO cell lines indicated that these genes may exhibit distinct gene interactions in NEPC compared to prostate adenocarcinoma." (PMID 37065756, 2023).
uterine cancer (1 paper, 2015). Primary or metastatic malignant neoplasm involving the uterine corpus and/or the cervix. "However, tissue and cancer-grade specific effects might be observed, as a recently published study revealed that ZBTB7A was commonly deleted in late stage oesophageal, bladder, colorectal, lung, ovarian and uterine cancers." (PMID 26187947, 2015).
uterine corpus endometrial carcinoma (1 paper, 2020). A endometrial carcinoma (disease) that involves the body of uterus. "However, the value for ZBTB7A in uterine corpus endometrial carcinoma (UCEC) is unclear." (PMID 33292231, 2020).
cancer (40 papers, 2008 to 2025). A tumor composed of atypical neoplastic, often pleomorphic cells that invade other tissues. "We found the ZBTB7A expression in TIMER was associated with various cancers, especially UCEC." (PMID 33292231, 2020). "LRF/ZBTB7A overexpression is also associated with enhanced cancer cell invasiveness and metastasis." (PMID 31823818, 2019). "Lastly, Zbtb7a has been strongly linked to cancer development and progression." (PMID 29813070, 2018). "The loss of ZBTB7A may be one of the significant potential mechanisms that causes cancer." (PMID 33292231, 2020). "However, LRF/ZBTB7A association with cancer progression goes far beyond hematological cancers." (PMID 31823818, 2019). "Zinc finger and BTB domain containing 7A (ZBTB7A) has been characterized as an oncogene across numerous cancer types." (PMID 39935428, 2025). "Previous studies reported that silencing of ZBTB7A induces G1 cell cycle arrest and a consequent reduction in the S phase population in various human cancer cell lines, implicating ZBTB7A in cellular processes such as proliferation, senescence and apoptosis." (PMID 37065756, 2023). "Previous studies described that ZBTB7A can exhibit opposing functions as a transcription factor, acting as a tumor suppressor or oncogene in different tissues and cancer types." (PMID 37065756, 2023). "Several studies have shown that silencing ZBTB7A induces apoptosis in cancer cells further sensitizing the cells to chemotherapies." (PMID 37065756, 2023). "This allowed us to identify ZBTB7A as a key factor in cancer cell survival from the broader set of NEPC-like cancer cell lines." (PMID 37065756, 2023). "We analyzed the target genes of ZBTB7A in ZBTB7A-knockdown cancer cells using the ChIP-Atlas database and predicted that the target gene binds to suppress tumorigenesis as a transcription factor." (PMID 36596853, 2023). "ZBTB7A, a transcriptional activator or repressor known to play an important role in tumorigenesis and metastasis in various human cancers, is downregulated in GBM25." (PMID 36596853, 2023). "Nonetheless, a deeper probe into the upstream regulatory mechanism of ZBTB7A in the cancer is warranted." (PMID 35012438, 2022). "There are studies in recent years investigated the role of ZBTB7A, which has been proved to play an oncogenic or tumor-suppressive role in multiple types of cancers." (PMID 35501800, 2022). "Among these overlapping genes, the HIC1 was significantly upregulated in ZBTB7A knockdown cells, and its well-known tumor suppressor gene plays a critical role in various cancers." (PMID 35501800, 2022). "ZBTB7A (zinc finger and BTB domain containing 7A) acts as a tumor suppressor through transcriptional repression in several carcinomas." (PMID 34395285, 2021). "The results showed that ZBTB7A expression negatively correlated with tumor purity in 2 cancer types (LUAD, READ)." (PMID 33292231, 2020). "ZBTB7A has been proved to be a critical factor for diagnosis, prognostication and prediction of treatment effect in multiple types of cancer." (PMID 33167891, 2020). "It is worth notable that the chromosomal region 19p13.3, including ZBTB7A, is often deleted in human cancer." (PMID 33292231, 2020). "Collectively, the data presented so far suggest that LRF/ZBTB7A is a pivotal factor regulating many different aspects of cancer progression." (PMID 31823818, 2019). "The dual roles of ZBTB7A controversially appear in a kind of cancer such as colorectal cancer and gastric cancer." (PMID 31309112, 2019). "Basing on the complex roles in multiply cancers, ZBTB7A is confirmed to be a significant target of prognosis and therapy." (PMID 31309112, 2019). "Recently, Zbtb7a was characterized as an oncogene in many types of cancers, which represses tumor suppressor ARF gene transcription." (PMID 28881782, 2017).